LINC01124 (long independently transcribed non-coding RNA 1124)
Gene: Long non-coding RNA gene on chromosome 2 (170,712,451 to 170,714,567, reverse strand). Ensembl gene ENSG00000222033.
Diseases named in the same sentence as LINC01124 in open-access papers:
LINC01124 is named in the same sentence as 3 diseases in open-access papers, as found by Europe PMC text mining. Sharing a sentence is not in itself a finding about the gene and the disease. The quoted sentences say what the papers report.
hepatocellular carcinoma (1 paper, 2021). A malignant tumor that arises from hepatocytes. "However, the expression and detailed role of LINC01124 in hepatocellular carcinoma (HCC) remain unestablished to date." (PMID 37304672, 2021).
tumor (3 papers, 2021 to 2024). "The expression level of LINC01124 was reported to be downregulated in tumor tissues compared with paired normal lung tissues, and LINC01124 significantly inhibited the proliferation, migration, and invasive ability of NSCLC cells." (PMID 36193129, 2022). "Overall, the miR-1247-5p/FOXO3 axis contributes to the tumor-promoting activities of LINC01124 in HCC cells." (PMID 37304672, 2021). "LINC01124, which is located at chromosome 2q31.1, was shown to act as a tumor suppressor in NSCLC." (PMID 36193129, 2022). "In summary, LINC01124 plays a tumor-promoting role in HCC by regulating the miR-1247-5p–FOXO3 axis." (PMID 37304672, 2021). "Additionally, ablation of LINC01124 resulted in tumor growth impairment in vivo." (PMID 37304672, 2021). "Additionally, LINC01124 ablation impaired tumor growth in vivo." (PMID 37304672, 2021).
cancer (2 papers, 2021). A tumor composed of atypical neoplastic, often pleomorphic cells that invade other tissues. "Several other lncRNAs, such as SERTAD4-antisense 1, LINC01124, AC011294.1 and RBPMS Antisense RNA 1, have also been associated with cancer initiation and prognosis." (PMID 34689838, 2021). "Thus, LINC01124 tissue specificity was confirmed in its expression profile and specific functions in human cancers." (PMID 37304672, 2021). "The proposed mechanism of the miR-1247-5p–FOXO3 axis may be helpful for better understanding the role of LINC01124 in HCC oncogenesis and promoting the identification of promising therapeutic strategies for cancer treatment." (PMID 37304672, 2021).